IL10 (interleukin 10)
Diseases named in the same sentence as IL10 in open-access papers (continued):
Sharing a sentence is not in itself a finding about the gene and the disease.
colitis (continued). "Immunomodulatory cytokine IL-10 deficient mice showed spontaneous development of colitis and had relatively higher proportion of Proteobacteria than wild-type mice." (PMID 33832437, 2021). "For example, a high-fat diet exacerbated intestinal inflammation in the IL-10-deficient colitis model." (PMID 34062869, 2021). "The adenosine receptor agonist IB-MECA was shown to alleviate inflammation in DSS-induced colitis and spontaneous colitis found in IL-10-deficient mice." (PMID 34158863, 2021). "It was also shown that docosahexaenoic acid (LCFA) reduced infiltration of inflammatory cells, lowered inflammation scores, decreased pro-inflammatory cytokines, and improved body weight in the model of colitis induced by IL-10 deficiency." (PMID 34444876, 2021). "Conventionally raised mice deficient for the anti-inflammatory cytokine IL-10 (encoded by Il10) develop colitis spontaneously." (PMID 34085924, 2021). "Since first description of mutations in genes Il-10RA and Il-10RB in patients with early-onset colitis in 2009, about 70 cases of Il-10/Il-l0R deficient patients with IBD phenotype have been identified." (PMID 33691712, 2021). "H. hepaticus predominantly induces inflammatory TH17 cells in disease-susceptible IL-10-deficient animals and contributes to spontaneous colitis." (PMID 32601832, 2021). "Previous studies have shown that the absence of L. reuteri leads to colic in infants, L. reuteri supplementation alleviates the damage of DSS-induced colitis in mice, and L. reuteri can be used to treat enteritis in IL-10-deficient mice." (PMID 34712207, 2021). "Resveratrol treatment has significantly reduced the symptoms of colitis in IL-10−/− mice such as weight loss and the serum level of the acute phase protein SAA, a well-documented biomarker for colitis severity." (PMID 34944544, 2021). "Hayashi and his colleagues demonstrated that Clostridium butyricum induces IL-10 production in macrophage-specific IL-10-deficient mice, which helps to prevent acute colitis." (PMID 34202945, 2021). "MIBE has been primarily investigated using E. faecalis as a pathobiont in the colitis-associated Il10 knockout (Il10−/−) murine model of CRC." (PMID 33969420, 2021). "In terms of CRC, numerous works have validated the association of E. faecalis with murine colitis and this type of cancer via the use of interleukin-10 (IL-10)-deficient mice." (PMID 34835352, 2021). "Resident enteric bacteria are necessary for the development of spontaneous colitis and immune system activation in IL-10-deficient mice." (PMID 35058894, 2021). "Its importance in the intestinal immune milieu is apparent in both mice and humans as IL-10 deficient mice develop spontaneous inflammation of the colon, and humans with mutations in IL-10 or IL-10 receptor (IL-10R) also develop colitis at an early age." (PMID 33717186, 2021). "Several genetically engineered animal IBD models, such as IL-10-deficient mice, spontaneously develop colitis, triggered by an excessive immune reaction against the commensal microbiota." (PMID 34062869, 2021). "Infection of colitis-susceptible Il10-deficient (Il10-/-) mice with CDT-deficient H. hepaticus or H. cinaedi resulted in less severe typhlocolitis (inflammation of the caecum and adjacent colon) compared with infection with the CDT wild-type isogenic strains." (PMID 34204481, 2021). "As defects in the IL-10R and IL-10 signaling on macrophages play a major role in causing severe colitis in patients, the generated VEO-IBD patient-derived iPSC clones were differentiated into macrophages for the detailed analysis of the IL-10RB defect." (PMID 33804706, 2021). "IL-10 deficient mice are a well-established IBD animal model due to the development of spontaneous colitis." (PMID 33807591, 2021). "Patients with identified mutations in Il-10 gene in the first 3 months of life presented with colitis with perianal lesions which was resistant to complex therapy approach (steroids, immunosuppression, anti-TNF-alfa agents)." (PMID 33691712, 2021).
colitis (continued). "Interleukin-10-deficient mice colitis is a multi-hit model of colitis which involves genetic factor, immune disturbances and alterations of gut microbiota." (PMID 33691712, 2021). "The increased number of microorganisms such as Enterobacteriaceae and adherent-invasive E. coli develops colitis in IL-10 deficient mice and provokes induction of inflammation leading to the cancer development." (PMID 34440615, 2021). "Mutation of gene encoding IL-10 is believed to play a role in the pathogenesis of early onset UC which is characterized by severe colitis in infancy and early childhood." (PMID 34140896, 2021). "For instance, mice deficient in IL-10 develop spontaneous colitis through an aberrant response to commensals." (PMID 34650568, 2021). "For example, grape seed extract supplementation was associated with enhanced mRNA expression of MUC2 in IL10-deficient mice model of colitis." (PMID 33806347, 2021). "In humans, polymorphisms in IL-10 have been found to be correlated with very early onset of colitis." (PMID 34239686, 2021). "More in detail, the administration of AON showed therapeutic effects to mice that were subjected to both acute and chronic DSS colitis and IL10-deficient mice, which spontaneously develop intestinal inflammation." (PMID 33807591, 2021). "Lentivirus vector encoding murine interleukin-10 (IL-10) showed promising results in suppressing the development and relapse of experimental murine colitis." (PMID 34592900, 2021). "In contrast, a recent study demonstrated that the intake of high levels of dietary simple sugars, including glucose, fructose, or sucrose, exacerbates colitis in dextran sodium sulfate (DSS)-induced colitis mice and IL-10-deficient mice." (PMID 34062869, 2021). "We previously demonstrated that IL-10−/− mice colonized with an H. hepaticus strain deficient in CDT production (HhCDT−) develop significantly attenuated colitis despite colonization at the same levels as for wild-type H. hepaticus (HhCDT+)." (PMID 34126769, 2021). "Il10-/- mice with colitis also have an increased risk of dysplasia and invasive colon cancer relative to control mice." (PMID 32941525, 2020). "The studies reported here show that TIA mice that are triply deficient in Il10, Tnf, and the APOBEC family mutator enzyme Aicda develop severe UC-like colitis soon after weaning, similar to T/I mice that are deficient in Tnf and Il10 alone." (PMID 32941525, 2020). "In the present study, the development of colitis and C. glabrata overgrowth were associated with high expression of IL-1β and down-regulation of IL-10." (PMID 32661259, 2020). "In a mouse colitis model, an induction of IL-10 upon FMT was observed, which was associated with the increased abundance of fecal SCFA-producing taxa, including Odoribacter." (PMID 33281770, 2020). "Several studies have shown the Treg involvement in colorectal tumorigenesis, e.g. IL-6 and IL-10 both enhanced tumorigenesis in colitis-associated cancer models, whereas blockade of IL17A inhibited tumor growth." (PMID 32677955, 2020). "Recent study indicated a pathogenic role of IL-22 in the model of spontaneous colitis in IL-10-/- mice, whereas other studies demonstrated a protective role for IL-22 in host defense against C. difficile and C. rodentium mucosal pathogens." (PMID 33488580, 2020). "Colitis in IL‐10−/− B and ManLAM‐ IL‐10−/− B group was characterized by a loss of crypts, infiltration of inflammation cells into the mucosa and submucosa, oedema of submucosa, erosion and ulceration." (PMID 31657484, 2020). "Mice on a C3H/HeJBir background are highly susceptible to disease compared to other IL-10-/- strains such as C57BL/6J which are resistant to the development of colitis." (PMID 33664728, 2020). "Pathogenic role of IL-17 in C. jejuni-induced colitis was previously implicated as IL-17 blocking antibody ameliorated intestinal inflammation in IL-10-/- mice." (PMID 33488580, 2020).
colitis (continued). "Colitis development in mice carrying mutation in Il10 gene starts shortly after weaning and is microbiota dependent, as germ-free mice do not develop any signs of inflammation." (PMID 33664727, 2020). "In keeping with this, colitis-prone IL-10-deficient mice exhibit a decline in vitamin D receptor (VDR) expression that correlates with colitis symptoms." (PMID 33042125, 2020). "For example, in murine spontaneous colitis models such as those utilizing Toll-like 5 receptor or interleukin-10 deficient mice, an overabundance of Proteobacteria was found to correlate with a heightened pro-inflammatory immune response." (PMID 32401750, 2020). "In animal models, mice genetically predisposed to colitis (IL-10−/−) are resistant to disease onset while being kept under germfree conditions, but clinical signs instigate immediately following exposure to microbes." (PMID 33024049, 2020). "Colitis development was associated with a gradual shift in the composition of the fecal bacterial microbiota (i.e., ‘dysbiosis’) in H. hepaticus-infected IL10−/− mice." (PMID 32286276, 2020). "Another study showed that mTORC1-deficient DCs displayed an increased susceptibility to DSS-induced colitis, suggesting that mTORC1 is essential in intestinal CD11c+CD11b+ DCs and is critical for regulating intestinal homeostasis by promoting IL-10 production." (PMID 32290362, 2020). "IL-10 has been critically linked to the prevention of colitis, as mice deficient in IL-10 or IL-10 receptor-chain 1 spontaneously develop colitis." (PMID 32762699, 2020). "The administration of apelin can enhance lymphatic function of intestinal tissues to ameliorate the progress of colitis in IL-10 deficient mice." (PMID 33334069, 2020). "QCHS and SASP significantly reduced the Th17/Treg ratio in the experimental colitis mice and downregulated the levels of the Th17 cell-associated cytokine IL-17 and increased the levels of the Treg-associated cytokine IL-10 and transcription factor Foxp3." (PMID 32967687, 2020). "IL-10 is another immunomodulatory cytokine with a central function in suppression of excessive inflammation finding expression in the fact that IL-10-deficient mice spontaneously develop colitis." (PMID 31955243, 2020). "IL-10-deficient mice develop spontaneous severe colitis and consequently CRC, which can be attenuated by IL-10 administration and antibiotic treatment." (PMID 32754267, 2020). "In the human microbiota associated IL-10-/- mice, the gut microbiota had been depleted as early as 3 weeks post-partum (i.e., upon weaning) in order to avoid colitis development due to the antigenic stimuli derived from the commensal gut microbiota." (PMID 32664563, 2020). "It was shown that mice deficient in either IL-10 or its receptor IL-10R develop spontaneous colitis." (PMID 33042131, 2020). "A similar effect was also observed for polysorbate-80 with a diminished abundance of butyrate-producing species and increase in a species of Bilophila, a hydrogen sulphide producer implicated in colitis in IL-10 knockout mice." (PMID 31853641, 2020). "IL-10 deficiency has been demonstrated to exacerbate colitis in the DSS-induced colitis model as IL-10−/− knockout mice develop spontaneous colitis." (PMID 32067099, 2020). "In a colitis-associated CRC model with 129/SvEv Il10-/- mice, a curcumin-supplemented diet enriched the order Lactobacillales (represented mainly by Lactobacillus) and depleted Coriobacterales." (PMID 32499711, 2020). "Thereby, our and other groups used genetically susceptible colitis mouse models (Rag1-, IL-2-, and IL-10-deficient) exhibiting a dysregulated immune system to mimic disease development in an immune suppressed host." (PMID 32038631, 2019). "Anderson and Rapport recently suggested a biomarker profile incorporating IL-17/IFN-γ/IL-10/TGF-β1/CRP based on findings from ipilimumab-associated colitis." (PMID 31293970, 2019).
colitis (continued). "For example, Il10−/− mice on a C3H/HeJBir or 129/SvEv background show higher colitis susceptibility than Il10−/− mice on C57BL/6J background." (PMID 31396223, 2019). "It was found that dietary histidine prevented the development of colitis in an IL-10-deficient murine model." (PMID 31011585, 2019). "Although the exact involvement of MGL-1 in the tumor growth remains elusive, expression of MGL-1 by macrophages has been associated with increased production of IL-10 and acquisition of an anti-inflammatory role in a mouse model of experimental colitis." (PMID 30476078, 2019). "We previously showed that murine norovirus (MNV) induces colitis in the Il10-deficient (Il10−/−) mouse model of IBD in a microbiota-dependent manner." (PMID 31396223, 2019). "In general, the induction of spontaneous colitis in Il10-/- mice is strongly associated with the gut microbial community." (PMID 31275292, 2019). "In the case of CRP, IL-6, IL-12, and IL-10, the addition of both beta-glucans to the feed of animals with induced colitis caused a statistically significant reduction of their level to the level observed in healthy control group (HβG−) or even lower." (PMID 31590413, 2019). "Colonization of GF Il10−/− mice, which are susceptible to inflammation due to deletion of the Il10 gene, with either pks+ or pks− E. coli results in the induction of severe colitis." (PMID 31703321, 2019). "Depending on the cytokine environment and immunological context, butyrate, acetate, and propionate, the most available SCFA in the gut, can also support IL-10 expression in Th1 and Th17 effector cells, thereby inhibiting colitis caused by pathogenic T cells." (PMID 31998303, 2019). "For example, high fat diet promotes the expansion of intestinal bacterium Bilophila wadsworthia and colitis in IL10-deficient mice." (PMID 31289620, 2019). "To assess the inflammatory potential of K. pneumoniae 51-5 in vivo, we performed mono-association studies in germ-free (GF) Il10−/− mice (129SvEv), a colitis model susceptible to bacteria colonization." (PMID 30833613, 2019). "Accordingly, a favorable effect of GSPE on the intestinal barrier function was found in a study performed with IL-10-deficient mice that develop spontaneous colitis." (PMID 31035432, 2019). "The genetic background of Il10−/− mice is an important factor that determines colitis susceptibility." (PMID 31396223, 2019). "Celastrol has been reported to ameliorate colitis in IL-10 deficient mice, which has clearly confirmed that celastrol up-regulated the autophagy of colon tissue in IL-10−/− mice by inhibiting the PI3K/Akt/mTOR signaling pathway." (PMID 30678689, 2019). "Here we demonstrate that colitis-susceptible Il10-deficient mice develop inflammation-associated fibrosis when monoassociated with adherent/invasive Escherichia coli (AIEC) that harbors the yersiniabactin (Ybt) pathogenicity island." (PMID 31481410, 2019). "During acute colitis, IL-10 secretion by APC and T cells upon FMT was temporally linked to the resolution of inflammation." (PMID 31142049, 2019). "It has been demonstrated that the microbial status modulates the development of colitis-associated CRC in the IL-10-deficient (Il10−/−) mouse model." (PMID 31772577, 2019). "Recent studies showed that GSE supplementation inhibited intestinal hyperpermeability and the expression of proinflammatory cytokines in IL-10-deficient colitis." (PMID 31689935, 2019). "To address the regulatory effects of specific oligosaccharides in colitis linked to the microbiota composition, we have supplemented interleukin-10 null (Il10-/-) mice with four fucosylated and sialylated oligosaccharides." (PMID 31275292, 2019). "After being colonized by the gut microbiota isolated from UC patients, germ-free interleukin 10-deficient mice emerged obvious colitis symptoms with a proinflammatory gene expression and a decrease in microbial diversity." (PMID 31354859, 2019).
colitis (continued). "Mice deficient in either IL-10 or IL-10R spontaneous develop colitis, but only after colonization with microorganisms, showing the essential role that IL-10 plays after activation of immune cells by PRRs." (PMID 31227842, 2019). "Deficiency in IL-10 leads to spontaneous development of aggressive autoimmune disease in adoptive transfer models of murine colitis." (PMID 32010704, 2019). "More severe inflammation was observed in colitis‐susceptible interleukin‐10 knockout (Il10‐/‐) mice." (PMID 31866761, 2019). "In patients with colitis and inflammatory bowel disease, damaged mitochondria accumulate in macrophages when IL-10 signal is deficient." (PMID 31341536, 2019). "An increase in B. wadsworthia mediated the colitis induced by a high saturated fat diet in IL-10-deficient mice." (PMID 31110701, 2019). "Macrophages unable to sense IL-10, due to loss of IL-10 receptor, play a central role in the development of severe spontaneous colitis." (PMID 31011585, 2019). "Such an effect triggers colitis in animals deficient in either interleukin-10, a cytokine exerting anti-inflammatory and regulatory functions, or Toll-like receptor 5, a receptor recognizing the bacterial flagellin." (PMID 31581570, 2019). "In our study, we showed that Th1/Th17 related cytokines, such as IFN-γ and IL-17 were markedly increased in rats in the MOD group, while the production of Th2/Treg associated cytokines TGF-β and IL-10 were reduces during the progression of colitis." (PMID 29973876, 2018). "Although colitis in IL10-deficient humans develops early in childhood, in Il10-deficient mice on pure C57BL/6J background, colitis only occurs in adult animals and in a milder form of disease than observed in other genetic backgrounds." (PMID 30410494, 2018). "IL-10 plays a major role in the maintenance of intestinal homeostasis; it is known that IL-10-deficient mice develop spontaneous colitis, while patients with a gene mutation in the IL-10 receptor develop severe IBD." (PMID 29164271, 2018). "Despite the clear link between low levels of IL-10 and susceptibility to colitis in human as well as in mouse models, administration of IL-10 to treat this condition showed only limited effects." (PMID 29545807, 2018). "Celastrol ameliorates colitis in IL-10-deficient mice by reducing colon myeloperoxidase concentration and inhibiting colonic pro-inflammatory cytokines via PI3K/Akt/mTOR signaling pathway." (PMID 29491837, 2018). "IL-10-deficient mice irrefutably develop colitis spontaneously and pathologically resemble human IBD." (PMID 29910812, 2018). "HFD had been consistently associated with increased abundance of B. wadsworthia, a bacterium implicated in increased colitis severity of Il-10-/- mice." (PMID 30022049, 2018). "Mutations in IL10 or the genes encoding its receptors IL10RA/IL10RB in humans were shown to cause autosomal recessive disease with CD-like colitis and GWAS studies have identified associations between these three genes and sporadic IBD." (PMID 30410494, 2018). "We crossed the DC-specific Tcf4 conditional knockout (CKO) strain with Il10-deficient mice (Il10−/−) that develop colitis resembling human IBD." (PMID 30410494, 2018). "Body weight loss in colitis and colitis-induced expression of Il6, Tnf, Il1β and Il10 were reduced in JHT mice." (PMID 29695802, 2018). "The genetically engineered models include IL-10-deficiency colitis, T-bet transgenic mice, and T-cell specific Blimp-1 deficiency colitis." (PMID 29518037, 2018). "Various clostridia species have also been reported to induce IL-10-producing Treg cells, and oral inoculation of these bacterial strains mediates amelioration of chemically induced colitis underlining the protective role of IL-10 in these models." (PMID 29124320, 2018). "While it has been shown that mast cell deficiency enhanced spontaneous colitis in the IL10−/− murine model, the precise role for mast cells in spontaneous colitis has yet to be fully determined." (PMID 29849494, 2018).